H19 (H19 imprinted maternally expressed transcript)
Diseases named in the same sentence as H19 in open-access papers (continued):
Sharing a sentence is not in itself a finding about the gene and the disease.
diabetes (continued). "This study identifies the lncRNA H19-HDAC6 axis as a significant regulator of cellular IRS1 levels and impaired levels of lncRNA H19 and HDAC6 alter IRS1 levels in the skeletal muscle during diabetes." (PMID 35842608, 2022). "In H19 OE and WT mice, streptozotocin (STZ) (50 mg/kg, ip) was injected continuously into the femoral vein for seven days to stimulate diabetes mellitus." (PMID 36044268, 2022). "Here, this study was designed to determine the relationship between long non-coding RNA (lncRNA) H19, mircoRNA29b (miR-29b), and VEGFA in the development of diabetes mellitus (DM)." (PMID 31737629, 2019). "Diabetes was followed by increased expression of α-SMA, fibronectin, and Col I. H19 expression was significantly up-regulated, whereas miR-17 expression was significantly reduced." (PMID 27391349, 2016). "Furthermore, H19 inhibition normalized HDAC6 levels and protected the muscles from diabetes-mediated insulin dysfunction." (PMID 40176927, 2024). "We did not observe any significant variation in H19 expression depending on the occurrence of hypertension, dyslipidaemia, diabetes, prediabetes, osteoporosis, goitre, nephrolithiasis, or colon polyps." (PMID 37189829, 2023). "Lastly, studies showed that H19 overexpression prevented glucose-induced EndMT through TGF-β signaling via a blockade of the MAPK–ERK1/2 pathway; this action is independent of miR-200b, a miRNA previously shown to regulate diabetes-induced EndMT." (PMID 37762249, 2023). "To conclude, our study identifies the lncRNA H19 as a critical determiner of cellular IRS1 levels and during diabetes, decreased levels of this lncRNA promotes an inhibition in IRS1 gene expression, possibly due to increased deacetylation mediated by HDAC6 in the skeletal muscle." (PMID 35842608, 2022). "However, this increased plasma H19 levels do not necessarily mean that it is promoting diabetes, and therefore detrimental." (PMID 35946958, 2022). "Interestingly, inhibition of H19 only altered miR-29a levels, not miR-29b or miR-29-c, and suppressed TGF-β/Smad signaling in order to regulate EndMT and renal fibrosis in diabetes." (PMID 34199672, 2021). "However, the potential role of circulating lncRNAs H19 and GAS5 in type 2 diabetes mellitus (T2DM) and diabetic retinopathy (DR) is not clear." (PMID 31999937, 2020). "Although another study found that the methylation level of H19-Igf2 imprint control region was increased in the embryonic day 14 fetus from diabetic mice, we found that the methylation level of H19 DMR was not affected by maternal diabetes in the 10.5dpc embryo." (PMID 24378208, 2013).
Beckwith-Wiedemann syndrome (48 papers, 2008 to 2025). Beckwith-Wiedemann syndrome (BWS) is a genetic disorder characterized by overgrowth, tumor predisposition and congenital malformations. "SOX-OCT binding site and CTCF binding site 3 in H19-ICR are the sequences in which mutations cause H19-ICR hypermethylation leading to Beckwith-Wiedemann syndrome-like overgrowth." (PMID 39623082, 2024). "Mutations or abnormalities in the H19 gene or its regulatory regions can lead to developmental disorders, such as Beckwith-Wiedemann syndrome (BWS), characterized by overgrowth and increased cancer risk." (PMID 38166752, 2024). "CTCF site-specific deletions were shown to be associated with imprinting in the IGF2/H19 locus, causing Beckwith-Wiedemann syndrome (BWS; OMIM 130650)." (PMID 33863876, 2021). "H19 ( = 39) was associated with 39 diseases, including Beckwith-Wiedemann syndrome, Silver-Russell syndrome and many types of cancer." (PMID 24498199, 2014). "IGF2 and H19 are both imprinted genes and loss of imprinting of the IGF2/H19 locus has been observed in the Beckwith-Wiedemann syndrome, a congenital overgrowth disorder." (PMID 24349121, 2013). "Accurate DNA methylation of the IGF2/H19 locus is important for growth and disorders of imprinting mediated by DNA methylation in this region (Russell Silver and Beckwith Wiedemann syndromes) are associated with clear phenotypes of altered growth." (PMID 23148549, 2012). "Since, a methylation defect at the Igf2/H19 locus can result in imprinting disorders, and has been associated with Beckwith-Wiedemann syndrome, such gene dysregulation as a result of higher maternal FA may modulate epigenetic abnormalities in the pathogenesis of growth and development." (PMID 25629700, 2015). "Dysregulation of the H19/IGF2 cluster is associated with two growth disorders, Beckwith-Wiedemann syndrome (BWS) and Silver-Russell syndrome (SRS)." (PMID 36441651, 2022). "In human, the phenotype related to the silencing of IGF2 is Silver Russell syndrome and H19 silencing is related to Beckwith Wiedemann syndrome." (PMID 23724794, 2013). "Aberrant imprinting of the IGF2/H19 locus on chromosome 11p15.5 has a crucial role in Beckwith-Wiedemann syndrome (BWS, OMIM #130650), Silver-Russell syndrome (SRS, OMIM#180860) and several human cancers." (PMID 22646060, 2012). "The overgrowth Beckwith-Wiedemann syndrome is associated with hypermethylation of the ICR, leading to increase of IGF2 and decrease in H19 activity." (PMID 23148549, 2012). "As an example, patients with Beckwith-Wiedemann Syndrome (BWS), linked to chromosome 11p15.5, have abnormal hypermethylation of the maternal H19 ICR, leading to higher expression of IGF2 with an overgrowth syndrome and increased cancer risk." (PMID 18414667, 2008). "Like H19, it is involved in Beckwith-Wiedemann syndrome, but its function in cartilage is still unknown." (PMID 36538560, 2022). "Similarly as for the H19 DMR—where epigenetic alterations that affect CTCF binding cause the growth-related imprinting disorders Beckwith-Wiedemann Syndrome (BWS) and Silver-Russell Syndrome (SRS) —maternal CTCF binding at the Meg3 DMR is evolutionarily conserved in humans." (PMID 31831055, 2019). "Similarly, loss of DNA methylation imprinting in long non-coding H19 and neighboring IGF2 in the placenta is associated with Beckwith-Wiedemann Syndrome and increased prenatal and placental growth." (PMID 25675430, 2015). "Notably, these cloned piglets with macroglossia were accompanied with the high methylation and expression levels of H19/Igf2, similar to Beckwith Wiedemann syndrome in human assisted reproduction." (PMID 25962071, 2015). "For example, hypermethylation of H19-DMR, which is the ICR of the IGF2/H19 imprinting domain at the 11p15.5 locus, is a cause of Beckwith-Wiedemann syndrome (BWS), the most common overgrowth syndrome characterized by occasional development of embryonal tumors, including hepatoblastoma." (PMID 24373183, 2013).
Beckwith-Wiedemann syndrome (continued). "Indeed, H19-DMR hypomethylation has led to SRS-like phenotype in a patient with parthenogenetic chimerism/mosaicism, whereas H19-DMR hypermethylation has resulted in Beckwith-Wiedemann syndrome-like phenotype in patients with androgenetic mosaicism." (PMID 23533668, 2013). "These functional associations of IGF2 and KCNQ1 rely on publications reporting how a differentially methylated region in KCNQ1 controls imprinted expression of other genes in the neighborhood and about epigenetic abnormalities in the IGF2/H19 region of Beckwith-Wiedemann syndrome patients." (PMID 23226257, 2012). "The absence of H19-mediated maternal imprinting may cause Beckwith-Wiedemann Syndrome (BWS) and correlates with an increased risk of developing a Wilms tumour of the kidney." (PMID 36428681, 2022). "Accordingly, it has been reported that hypermethylation at H19/IGF2:IG-DMR is present in the premalignant clonal expansions of WTs, representing an early event in Wilms tumorigenesis, and as constitutional epimutation in the Beckwith-Wiedemann syndrome cases with high predisposition to WTs." (PMID 33217932, 2020). "Hypermethylation at the H19 DMD is found in 30% cases of Beckwith Wiedemann syndrome (BWS), and the overgrowth macroglossia and organomegaly associated with this disorder may be caused by an increase in IGF2 transcription as a result of its biallelic expression." (PMID 20617174, 2010). "By contrast, hypermethylation of H19 ICR leads to overexpression of IGF2, downregulation of H19, and consequently fetal over-growth known as Beckwith-Wiedemann syndrome." (PMID 29946374, 2018). "DNA methylation abnormalities of the H19/IGF2:IG-DMR cause contrasting growth disorders (i.e., Beckwith-Wiedemann syndrome (BWS, MIM#130650) and Silver-Russell syndrome (SRS, MIM#180860)), if they are present on the maternal or paternal chromosome, respectively." (PMID 29484033, 2018). "In addition, research on the epigenetic mechanisms underlying Beckwith-Wiedemann Syndrome (BWS) and Silver-Russell Syndrome (SRS) has shown that methylation of the H19 gene exerts a pronounced effect on disease and muscle development." (PMID 27107967, 2016). "Like H19, KNCQ1OT1 is also located at 11p15.5, paternally imprinted, and its over-expression is associated with cancer progression, increased proliferation, and the overgrowth disorder Beckwith-Wiedemann Syndrome (BWS) via the inhibition of p57 expression." (PMID 24305655, 2013). "In developmental syndromes, such as Beckwith-Wiedemann syndrome, dysregulation of the H19/insulin-like growth factor 2 (IGF2) imprinting control region leads to H19 downregulation and IGF2 overexpression, driving embryonic cell overgrowth and differentiation defects." (PMID 40259926, 2025). "The hypermethylation of the H19 DMR and/or hypomethylation of the KvDMR1 may result in the Beckwith-Wiedemann syndrome (BWS)." (PMID 28881852, 2017). "Beckwith-Wiedemann syndrome (BWS, OMIM 130650), either sporadic (>85%) or familial (<15%), is caused by mutation or deletion of imprinted genes CDKN1C, H19 and LIT1 as well as by hypermethylation in the H19/IGF2-imprinting control region within the chromosome 11p15.5 region." (PMID 29190888, 2017). "In case of Beckwith-Wiedemann syndrome, demethylation of the IGF2/H19 imprinting control region leads to the binding of CTCF and subsequently blocks the connection between an enhancer for IGF2 and promotes activation of maternal H19." (PMID 25340699, 2014). "For example, Beckwith-Wiedemann Syndrome (BWS) with RMS involves dysregulation or alteration of imprinted genes in the 11p15.5 chromosomal region, including IGF2, H19, and CDKN1C (p57/KIP2)." (PMID 26420980, 2015). "Additionally, several cases of familial Beckwith-Wiedemann syndrome (BWS), with and without Wilms' tumors, have been shown to be caused by microdeletions of the methylation-specific CTCF binding sites in the H19 ICR, a rare familial cancer syndrome linked to epigenetics." (PMID 19305507, 2009).
ischemic stroke (48 papers, 2015 to 2025). A stroke disorder caused by obstruction of blood flow to the brain, due to thrombotic (local blood clot formation) or embolic (due to a blood clot or other material traveling from another site) event. "A separate study also revealed that patients with IS who exhibited increased plasma concentrations of H19 had a heightened risk of aspirin resistance, potentially leading to recurrent ischemic strokes." (PMID 39161158, 2024). "Compared to other lncRNAs, lncRNA H19 exhibited higher diagnostic sensitivity (0.89, 95% CI: 0.80–0.98) and specificity (0.96, 95% CI: 0.87–1.00), indicating that lncRNA H19 had relatively high diagnostic performance for ischemic stroke." (PMID 39766887, 2024). "Studies have found that an upregulated H19 level in plasma and exosomes was associated with poor prognosis in patients with ischemic stroke." (PMID 39204113, 2024). "This study explored the cerebroprotective effects of H19 knockdown in ischemic stroke and its underlying mechanisms." (PMID 39161158, 2024). "Compared to healthy controls, the level of circulating H19 was considerably higher in ischemic stroke patients, demonstrating high diagnostic specificity and sensitivity." (PMID 39021183, 2024). "H19 polymorphisms were associated with ischaemic stroke, and ischaemic stroke patients have higher levels of circulating H19." (PMID 37310201, 2023). "A study showed that compared with the CC+CT genotype of H19 rs217727, the TT genotype was associated with a 1.519-fold increased risk of ischemic stroke." (PMID 36275741, 2022). "A clinical study has found that the Rs217727 polymorphism of the lncRNA H19 gene is closely related to susceptibility to ischaemic stroke and can be used as a potential marker of ischaemic stroke." (PMID 35815278, 2022). "Currently, a small number of studies have begun to address the association of H19 genetic variants with ischemic stroke risk." (PMID 36275741, 2022). "Recently, studies have found that lncRNAs TUG1, SNHG14, H19, Gm4419, and 1810034E14Rik are associated with the prognosis of ischemic stroke by regulating cell apoptosis and inflammation." (PMID 34707480, 2021). "One of our studies demonstrated that circulating lncRNA H19 levels were negatively associated with the long-term neurological deficit recovery of patients with ischemic stroke." (PMID 33192490, 2020). "Genetic variants in H19 have been demonstrated to play a key role in ischemic stroke and coronary artery disease." (PMID 31275455, 2019). "The result from blood samples of ischemic patients revealed that the variation of H19 gene increased the risk of ischemic stroke." (PMID 28203482, 2017). "The modified multiple ligase reaction was used to analyze the gene polymorphism of six SNPs in H19, rs217727, rs2067051, rs2251375, rs492994, rs2839698 and rs10732516 in ischemic stroke patients." (PMID 28203482, 2017). "Additionally, previous research by our team linked increased plasma H19 concentrations to a higher risk of aspirin resistance and recurrent ischemic stroke." (PMID 39161158, 2024). "Additionally, the rs217727 variant in H19 was linked to ischemic stroke susceptibility and a higher risk of ischemic stroke." (PMID 39021183, 2024). "Most notably, H19 rs217727 polymorphism has been associated with susceptibility to type 2 diabetes in Iranian population and ischemic stroke in Chinese population.rs2839698 is another SNP within H19 whose association with cancer susceptibility has been assessed in recent years." (PMID 37326896, 2024). "The different values of H19 rs217727 were related to the higher risk of ischemic stroke." (PMID 38255915, 2024). "Furthermore, foundational studies have illuminated the critical role of lncRNA H19 in the intricate pathophysiological processes associated with ischemic stroke." (PMID 39204113, 2024). "Moreover, we observed miR‐29b downregulation in the neutrophils of ischemic stroke patients, which was negatively associated with H19 levels." (PMID 35322553, 2022).
ischemic stroke (continued). "Variation in H19 alleles, such as rs217727, has been shown to increase ischemic stroke risk." (PMID 34044272, 2021). "It has been proved that H19 polymorphisms correlate with the susceptibility ischemic stroke." (PMID 33193379, 2020). "We recently showed that H19 polymorphisms increase susceptibility to ischemic stroke." (PMID 33101034, 2020). "Also, a clinical study analyzed the correlation between H19 expression and risk for ischemic stroke in the Chinese Han population." (PMID 33192490, 2020). "Greater susceptibility to ischemic stroke could be linked to the expression of TT genotype rs217727 in H19." (PMID 33192490, 2020). "We also determined that H19 is an independent risk factor for ischemic stroke and that it could diagnose aspirin resistance with high specificity and sensitivity." (PMID 33101034, 2020). "Based on blood analyses, H19 gene variation increases the risk of ischemic stroke." (PMID 30967760, 2019). "Analysis of H19 gene polymorphism in the blood sample of stroke patients revealed that C to T variation of rs217727 and C to A variation of rs4929984 in H19 gene increased the risk of ischemic stroke." (PMID 28203482, 2017). "Moreover, H19 rs217727 bears significant potential as a biomarker for the risk of ischemic stroke." (PMID 33192490, 2020). "H19 can cause neuroinflammation by affecting histone deacetylase 1-dependent M1 microglial polarization and may be an important target for the therapy of ischemic stroke." (PMID 30778327, 2019). "Similarly, elevated H19 levels have been implicated in the setting of ischemic stroke." (PMID 31170091, 2019). "Furthermore, H19 knockdown attenuated brain tissue loss and neurological deficits 14 days post-stroke by promoting neuroinflammation to drive microglial polarization, suggesting a potential diagnosis and therapy for ischemic stroke." (PMID 30967760, 2019). "We thus speculated that the polymorphism of H19 was associated with the risk of ischemic stroke." (PMID 28203482, 2017). "A recent study has unveiled a compelling link between the genetic variation of the lncRNA H19 and the occurrence of ischemic stroke." (PMID 39204113, 2024). "They found that lncRNA H19 expression was increased in both in vitro and in vivo models of ischemic stroke." (PMID 39021183, 2024). "In the pathogenesis of ischemic stroke, lncRNA H19 regulates ACP5 expression by interaction with ACP5." (PMID 39766887, 2024). "Exosomes carrying H19 disrupt the BBB in ischemic stroke due to the interaction between H19, miR-18a, and VEGF." (PMID 39450275, 2024). "According to the mentioned studies, lncRNA H19 can be considered a new potential therapeutic candidate for ischemic stroke." (PMID 39021183, 2024). "Due to the activation of autophagy alongside the upregulation of lncRNA H19, they concluded that lncRNA H19 damages cell viability by activating the autophagy process during ischemic stroke." (PMID 39021183, 2024). "Studies have reported that circulating levels of lncRNA H19 are increased in ischemic stroke patients, and targeted inhibition of H19 can alleviate neurological deficits and reduce cerebral infarction volume in MCAO/R rats." (PMID 39766887, 2024). "A similar mechanism of action of H19 has been documented in studies of neurogenesis after ischemic stroke." (PMID 37628760, 2023). "For instance, it has been observed to be involved in neuroinflammation upon ischemic stroke (IS), where H19 reportedly competes with miR-138-5p to stimulate the NF-κB pathway, thus augmenting the release of pro-inflammatory cytokines." (PMID 38001964, 2023). "LncRNA H19, as a crucial member of the lncRNA family, plays an important regulatory role in the pathophysiological processes of ischaemic stroke, such as oxidative stress, the inflammatory response, apoptosis, autophagy, and neurogenesis." (PMID 35815278, 2022).